APOE (apolipoprotein E)
Diseases named in the same sentence as APOE in open-access papers (continued):
Sharing a sentence is not in itself a finding about the gene and the disease.
diabetes (continued). "Streptozotocin induced diabetic ApoE−/− mouse is a well characterized animal model of diabetes accelerated atherosclerosis." (PMID 24710090, 2010). "When adjusted for age, sex, education, diabetes, APOE genotype, folate, and vitamin B12 (Model 1), the ORs remained significant for both age groups, but the OR for the younger group was slightly higher than that for the older group (6.3 versus 4.2)." (PMID 20798752, 2009). "Age, sex, race-center, education, and APOE ɛ4 genotype, alcohol use, estimated glomerular filtration rate, body mass index, blood pressure, high density lipoprotein cholesterol, total cholesterol, hypertension, and diabetes." (PMID 40735554, 2025). "Age, sex, education, APOE ε4, alcohol, smoking, cholesterol, stroke, hypertension, diabetes, BMI." (PMID 41262081, 2025). "These include education, hearing loss, traumatic brain injury, hypertension, alcohol use, obesity, smoking, depression, physical inactivity, diabetes, low‐density lipoprotein (LDL) cholesterol, social isolation, air pollution, and untreated visual loss, as well as apolipoprotein E ε4." (PMID 41263327, 2025). "However, except for MMSE and CDR, the effect sizes for age, sex, education, APOE genotype, diabetes, and hypertension were small to moderate." (PMID 40547941, 2025). "Metabolic pathway analysis indicated that APOE+ fibroblasts might play a role in the onset and progression of diabetes through the Drug Metabolism-Cytochrome P450 pathway." (PMID 40612951, 2025). "In adjusted models, NHB and Hispanic ethnicity, APOE ε4, diabetes, hypertension, and tobacco dependence each independently predicted lower performance across all four cognitive domains (adjusted p < .001), whereas obesity showed domain-specific positive associations." (PMID 41035086, 2025). "AD is a multifactorial condition associated with various risk factors, including genetic mutations in proteins such as apolipoprotein E (APOE) and triggering receptors expressed on myeloid cells 2 (TREM2), alongside age, cardiovascular disease, obesity, and diabetes." (PMID 39936960, 2025). "The associations held for divorced and never‐married older adults after controlling for age, sex, race, ethnicity, education, living alone, depression, smoking behavior, diabetes, hypertension, obesity, diagnostic form, participant's referral source, reason to visit ADRC, and APOE ε4." (PMID 40110684, 2025). "Future studies on more diverse neurodegenerative cohorts might be valuable for generalizability of results and to evaluate the potential association between APOE, BBB integrity, prediabetes, and diabetes." (PMID 39992249, 2025). "Additionally, ApoE-/- mice with streptozotocin-induced diabetes were used to determine the effects of imeglimin in vivo by analyzing metabolic parameters and atherosclerotic plaque formation." (PMID 40214426, 2025). "After adjusting for age, sex, education, right handedness, APOE ε4, hypertension, diabetes mellitus, hyperlipidemia, smoking, atrial fibrillation, and heart failure, the cross-sectional analysis revealed no statistical association between IHD and cognitive measures (p > 0.05 for all)." (PMID 40015755, 2025). "Furthermore, both CVD and AD share several common risk factors, which increases the development of both diseases, including age, smoking, hypertension, hypercholesterolemia, diabetes mellitus, and apolipoprotein E (APOE) ɛ4 carriership." (PMID 38489178, 2024). "We hypothesize diabetes in ApoE knockout (ApoE-/-) mice induces cardiac dysfunction by increasing inflammation and necroptosis." (PMID 38390337, 2024). "This study aims to investigate the significance of APOE gene isoforms in CAN regardless of the presence of diabetes to identify the risk factors for this condition among individuals of Kazakh nationality." (PMID 39272762, 2024).
diabetes (continued). "Further analyses examined whether racial differences in the rate of change of plasma Aβ were modified by baseline amyloid status, age, sex, APOE ε4 carrier status, years of education, cognitive status, BMI, hypertension, or diabetes." (PMID 38956096, 2024). "Further analyses examined whether racial differences in the adjusted mean levels of plasma Aβ were modified by amyloid status, age, sex, APOE ε4 carrier status, years of education, cognitive status, BMI, hypertension, or diabetes." (PMID 38956096, 2024). "APOE and PILRA have been previously linked to diabetes, a condition that may be comorbid with allergic diseases." (PMID 38773393, 2024). "We provide strong evidence that pro-inflammatory cytokines, upregulated necroptosis cell death, and increased tissue infiltrating inflammatory monocytes and macrophages in the heart delineating adverse cardiac remodeling, exacerbating diabetes-induced cardiac dysfunction in ApoE KO mice." (PMID 38390337, 2024). "However, after adjusting for age, BMI, APOE genotype, history of diabetes, history of hypercholesterolemia, and history of hypertension, the statistical significance of the LBP index diminished (β = 0.39, p = 0.147)." (PMID 38882697, 2024). "In addition to the established risk factors for smoking, diabetes, and hyperlipidemia, female patients with CSFP exhibited significant differences in apoE, FFA, FT4, and TT4 levels compared to the control group." (PMID 38787982, 2024). "Analyses also examined whether factors such as sex, APOE ε4 carrier status, cognitive status, or medical conditions (hypertension and diabetes) modified potential racial differences." (PMID 38956096, 2024). "Disease duration, ApoE genotype, body mass index, constipation, and diabetes were evaluated." (PMID 37144597, 2023). "It is suggested that APOE ε4 carriers are associated with retinal vascular pathology independent of diabetes and hypertension; individuals with APOE ε4 showed blot hemorrhages, indicative of blood–retina barrier damage." (PMID 37685715, 2023). "We postulate that the elevated expression of ApoE in macrophages of individuals afflicted with obesity and diabetes may influence the regulation of chronic inflammation-associated glucose and lipid metabolism." (PMID 38062308, 2023). "Several clinical studies have not been able to establish a strong link between AD and diabetes, except in the case of carriers of the apolipoprotein E (ApoE) ε4 allele who are twice as likely to develop AD as those without diabetes." (PMID 38139841, 2023). "While the most prominent risk factor for AD is age, family history, variant ε4 of the apolipoprotein E (APOE-ε4) gene, hypercholesterolemia, type-2 diabetes mellitus, and traumatic brain injury are emerging as important and sometimes modifiable risk factors for the disease." (PMID 37569871, 2023). "We found here that ε4‐carried T2DM patients showed elevated GSK‐3β activity in periphery blood, which was positively correlated with diabetes duration, plasma HbA1c, and FPG level, which provided novel information to link ApoE gene polymorphisms and GSK‐3β with cognitive functions in T2DM patients." (PMID 37700547, 2023). "The current miRNA analysis has several limitations due to underpowered study design that would consider more adequate inclusion and stratification of other co-morbidities of AD, such as diabetes, cerebrovascular disease, and other factors, such as sex differences and ApoE genotypes." (PMID 37194065, 2023). "While there is growing evidence to support a link between the gut microbiome and brain health in aging, the specific associations between microbiome composition, brain imaging features, APOE genotype, BMI, diabetes, and dietary intake remain unclear." (PMID 37736325, 2023). "Therefore, in our study, we only used the ApoE KO male mice as a model for evaluating the relation between STZ-induced diabetes and ARHL." (PMID 36408520, 2022).
diabetes (continued). "Therefore, age, gender, education, APOE ε4 status, hypertension, diabetes mellitus, and cardiovascular disease were included as covariates in subsequent analyses." (PMID 36139790, 2022). "Unadjusted Model: MedDiet Score; Fully Adjusted Model: MedDiet Score, age, education, family history, APOE, physical activity, smoking, sleep, BMI, hypertension, hypercholesterolemia, hyperglycaemia, diabetes, stroke, antihypertensive medication use, diabetic medication use, Mediterranean region." (PMID 36568511, 2022). "Immunohistochemical fluorescence assay revealed that the levels of NLRP3, ASC, and GSDMD were significantly increased in the ApoE−/− mice following induction of diabetes and consistent feeding with a Western diet compared with the ApoE−/− mice fed with a control diet." (PMID 36425580, 2022). "Unadjusted Model: MedDiet Score; Fully Adjusted Model: MedDiet Score, sex, age, education, family history, APOE, physical activity, smoking, sleep, BMI, hypertension, hypercholesterolemia, hyperglycaemia, diabetes, stroke, antihypertensive medication use, diabetic medication use." (PMID 36568511, 2022). "Therefore, STZ injection successfully induced diabetes in ApoE KO male mice with marked increase in the blood glucose levels and modification of the islet's structure." (PMID 36408520, 2022). "For R2* iron in basal ganglia and in the cortex we estimated first, the heritability, second, the amount of variance that was explained by APOE ε4 carrier status, BMI, diabetes, hypertension, hypercholesterolemia and smoking and third, the genetic correlation between brain regions." (PMID 35951362, 2022). "Population selection in control groups failed to avoid certain diseases which might have a relation with the APOE gene, such as dyslipidemia, hypertension, other vascular diseases, and diabetes." (PMID 35154509, 2022). "The odds of showing a carotid plaque were 4.29 times higher (95% CI 1.16, 15.91, p < 0.05) among those participants genotyped as APOE e4e4 than those genotyped as APOE e3e3 after adjusting for BMI, hypertension, dyslipidemia, diabetes, MVPA, VO2max, and aMED score." (PMID 36357490, 2022). "Notably, atherosclerotic plaque morphology in diabetic ApoE−/− mice, characterized by hyperglycaemia and hyperlipidaemia, mimics the situation observed frequently in cardiac patients with diabetes mellitus." (PMID 35889743, 2022). "After additional adjustment for potential confounders (education, initial cognitive stage, APOE ε4 carrier, cortical thickness, hypertension, diabetes mellitus, dyslipidemia, and BMI), NFL tertile, baseline MMSE score, and Aβ positivity remained as significant predictors." (PMID 34996525, 2022). "Hence, ApoE−/− are the most suitable model currently for studying the diabetes-induced vascular injury." (PMID 34006831, 2021). "This relationship was not explained by age, sex, education, APOE-ε4 allele status, hypertension, diabetes, cognitive status, or white matter hyperintensity (WMH) volume." (PMID 34366799, 2021). "While the associations with diabetes and aspirin are consistent with the lower level of CRP found in APOE-ε4 carriers, their effects are unexpected in that diabetes and high levels of CRP have been reported as associated with an elevated risk of neurodegenerative diseases." (PMID 34301914, 2021). "In addition, CTRP9 inhibited hyperglycemia-induced vascular senescence and reduced atherosclerotic plaque formation in ApoE KO mice with STZ-induced diabetes." (PMID 34744738, 2021).
diabetes (continued). "In contrast, the ALT-increasing allele rs58542926-T (TM6SF2) is associated with lower risk of dyslipidemia, the ALT-increasing rs429358-T (APOE) is associated with lower risk of ischemic heart disease and the AST- and ALP-increasing allele rs1260326-T (GCKR) associated with lower risk of diabetes." (PMID 33547301, 2021). "While triglycerides, APOE variant, hypertension, hypercholesterolemia, and diabetes were significant predictors, this did not affect the relationship between rs9923231 and VaD." (PMID 33682710, 2021). "Finally, we demonstrate that these findings remain after adjusting for APOE genotype, as well as recognised health and lifestyle factors (diabetes, hypertension, smoking, and alcohol misuse)." (PMID 34924033, 2021). "However, the effects of ApoE go far beyond these diseases because this protein can affect a number of diseases, such as fertility, diabetes, and obesity." (PMID 34867826, 2021). "For instance, some studies have reported that VRFs (e.g., diabetes) could interact with APOE ε4 to adversely affect global cognitive function and specific cognitive domains, such as memory and executive function." (PMID 33790814, 2021). "In an ADRC- and community-based sample comprised of 135 participants, investigators reported that CSF-derived NfL levels were lower in cognitively normal AA compared to nHW after adjustment for age, sex, APOE-ε4 allele status, ABCA7 risk allele status, Aß-42, hypertension, diabetes, and WMH volume." (PMID 34366799, 2021). "Then by using the partial correlation analysis and controlling gender, we found that APOE E4 was associated was hyperlipidemia (r = − 0.154, p = 0.008), but not with hypertension or diabetes (p > 0.05)." (PMID 34285334, 2021). "Furthermore, APOE-ε4 dosage is strongly associated with lower levels of C-reactive protein (CRP), a lower incidence of diabetes and reduced regular use of aspirin." (PMID 34301914, 2021). "Our findings suggested that total cholesterol, triglyceride, ApoB, and ApoE were significantly correlated with the degree of LFC in MAFLD patients with obesity or diabetes, while stepwise increase in LDL-c and FFA was only associated with higher LFC in those with obesity/overweight." (PMID 34899591, 2021). "The effect remained significant for both ADem (OR = 1.29, 95% CI = 1.08–1.53, p = 4.5×10–3) and VaD (OR = 2.17, 95% CI = 1.74–2.69, p = 1.9×10–12) when APOE status, triglycerides, and diagnoses of hypercholesterolemia, hypertension, and diabetes were included in the model as covariates." (PMID 33682710, 2021). "Second, it is possible that although the pathobiological detrimental effects of APOE ε4, hypertension, diabetes, and dyslipidemia still exist at younger ages, they might be overshadowed by other yet unknown genetic or environmental factors." (PMID 34127075, 2021). "Indeed, inhibition of RAGE in diabetic ApoE knockout (ApoE KO) mouse showed attenuation of diabetes induced atherogenesis via deactivation of AGE-RAGE signaling and reduction in oxidative stress." (PMID 34829831, 2021). "Moreover, the induction of diabetes was associated with an ~2-fold and 1.5-fold increase in kidney to body weight ratio compared to both chow and western diet fed mice for C57BL/6 and apoE KO mice respectively (p < 0.0001)." (PMID 32581831, 2020). "For each sample, we performed a proportional hazards regression analysis considering conversion time as time; “conversion to AD” as dependent variable; and age at onset, age at baseline, ApoE genotype, hypertension, diabetes, dyslipidemia, heart disease, and smoking habit as covariates." (PMID 32485802, 2020). "Results of the regression analyses on the association between MDW and hippocampal and brain volume, separate for those that are retired and those that are not retired, adjusted for age, gender, education, APOE e4-allele, hypertension, and diabetes." (PMID 33536897, 2020).
diabetes (continued). "Apolipoprotein E (ApoE), a constituent of the deposits, has been identified in the islet cells as having a significant role in disorders of lipid metabolism, which are often related with diabetes." (PMID 32503113, 2020). "Next, the role of NLRP3 in endothelial cells in the development of diabetes-associated AS was assessed in endothelial cell-specific NLRP3 mutant, ApoE (-/-) mice (APOEKO/Tie2p-Cre/NLRP3MKO), compared to control ApoE (-/-) mice (APOEKO), supplied with either high-fat diet (HFD), or normal diet (ND)." (PMID 32966239, 2020). "For Nox4, both possibilities, protection and lack of protection from albuminuria, have been reported for diabetic animals, which could be due to the use of different diabetes models (i.e., streptozotocin-induced versus ApoE knockout mice)." (PMID 32635630, 2020). "Next, the role of NLRP3 in endothelial cells in the development of diabetes-associated AS was assessed in endothelia-specific NLRP3 mutant, ApoE (-/-) mice (APOEKO/Tie2p-Cre/NLRP3MKO), compared to control ApoE (-/-) mice (APOEKO), supplied with either HFD, or normal diet (ND)." (PMID 32966239, 2020). "Moreover, feeding of a western diet resulted in a greater elevation in plasma triglyceride levels than did the induction of diabetes in apoE KO mice (p < 0.01)." (PMID 32581831, 2020). "Furthermore, to our knowledge as previously unreported findings, apoE ε4 also associated with altered levels of certain previously identified novel risk biomarkers of CAD, inflammation, diabetes and all-cause mortality." (PMID 30679475, 2019). "The apolipoprotein E (APOE) polymorphisms are associated with cardiovascular (CV) disease, but its interaction with type 2 diabetes mellitus (T2DM) long-term incidence is unknown." (PMID 31485353, 2019). "In addition, the prevalence of CAD in diabetes patients varied according to different APOE genotypes, which was 81% in ε4 patients, 58% in E3/3 patients and 53% in E2/2 or E2/3 patients." (PMID 31521122, 2019). "At present, it is known that ApoE isoforms differentially regulate Aβ aggregation and clearance in the brain and have distinct functions in regulating several other pathologies involved in AD including diabetes." (PMID 29510495, 2018). "In addition, the Honolulu-Asia Aging Study using rigorous phenotyping of diabetes has found greater risk of AD pathology in T2DM patients, but only among those carriers of APOE ε4 allele." (PMID 30364261, 2018). "Thus, it remains difficult to distinguish between the lipid dependent and lipid independent roles of ApoE in diabetes." (PMID 30303984, 2018). "A cross-sectional study was carried out to explore the relationship among ApoE gene polymorphism, diabetes and cognition in non-demented aging Chinese adults." (PMID 29896424, 2018). "Interestingly, the gene expression pattern in GEO profiles of diabetes models in both mouse and human reveal a differential expression of ApoE levels during diabetes, and reveal an important connection between ApoE and diabetes." (PMID 30303984, 2018). "Finally, we did not observe any effect modification of chronic ailments such as cancer, impaired cognitive function, diabetes, ischemic heart disease, and cerebrovascular disease with APOE genotype on longevity." (PMID 29770230, 2018). "We recently described that the streptozotocin induced diabetic apoE mouse model, which faithfully recapitulates the renal changes in diabetes, is characterized by macrophage activation, which may explain the increased NO availability." (PMID 28103268, 2017). "Indeed, regulation of the Glo1 enzyme has been proved to be important in prevention of early renal impairment in experimental diabetes, but also independently of hyperglycaemia in apoE−/− mice." (PMID 28106778, 2017). "Other diabetes-specific proteins were ApoE, Timp3, fibrillin, fibronectin, and PRELP." (PMID 29284024, 2017). "CE prevented dietary-induced diabetes in ApoE−/− mice by increasing the insulin secretion." (PMID 28091547, 2017).